OVOL1 (ovo like transcriptional repressor 1)
Diseases named in the same sentence as OVOL1 in open-access papers (continued):
Sharing a sentence is not in itself a finding about the gene and the disease.
metastatic colorectal cancer (1 paper, 2021). "Here, we found that GRHL2, ELF3, and OVOL1 were overexpressed in the CTC lines compared with SW620 cells (metastatic colorectal cancer cell line), particularly GRHL2." (PMID 34771571, 2021).
nasopharyngeal carcinoma (1 paper, 2017). A carcinoma arising from the nasopharyngeal epithelium. "ZIC2 and OVOL1 may function in nasopharyngeal carcinoma through targeting significantly up-regulated genes (such as PTGS2, FN1, CXCL9 and CXCL10) in the Transcription factor-differentially expressed gene regulatory network (e.g., ZIC2→PTGS2 and OVOL1→CXCL10)." (PMID 27765529, 2017). "PTGS2, FN1, CXCL9, CXCL10, ZIC2 and OVOL1 might play roles in nasopharyngeal carcinoma." (PMID 27765529, 2017).
ovarian carcinoma (1 paper, 2025). A malignant neoplasm originating from the surface ovarian epithelium. "While in oral SCC and ovarian carcinoma, downregulation of OVOL1 paralleled disease progression and metastatic potential." (PMID 41230293, 2025). "Similar findings have been reported in breast and ovarian carcinomas, where OVOL1 downregulation correlated with higher histologic grade and more aggressive phenotypes." (PMID 41230293, 2025).
renal cell carcinoma (1 paper, 2025). "In renal cell carcinoma, low OVOL1 expression was significantly correlated with advanced TNM stage, poorer prognosis, and served as an independent prognostic factor." (PMID 41230293, 2025).
salivary gland tumors (1 paper, 2025). "In addition, integrating clinicopathological correlations provided valuable insights into the potential diagnostic and prognostic relevance of OVOL1 in salivary gland tumors." (PMID 41230293, 2025).
ZIKV infection (1 paper, 2023). "We observed a down-regulated expression of GCM1, OVOL1, ERVW-1, and ERVFRD-1 in hTSCs following ZIKV infection." (PMID 37684223, 2023).
cancer (21 papers, 2011 to 2025). A tumor composed of atypical neoplastic, often pleomorphic cells that invade other tissues. "Ovol1 has been shown to induce mesenchymal to epithelial transition in human cancers and is associated with rs3903072." (PMID 35087569, 2021). "OVOL1, encoding a zinc finger protein, is expressed in embryonic epidermal progenitor cells and is an inducer of mesenchymal-to-epithelial transition in human cancers." (PMID 29686831, 2018). "Although OVOL1's impact on cancer advancement has been documented, its role in regulating cholesterol metabolism, especially in NSCLC, has not been well studied." (PMID 40437660, 2025). "The discovery of OXCT1 and OVOL1 as metabolic and transcriptional regulators of gemcitabine sensitivity has broader implications in other gemcitabine-treated cancer types." (PMID 39509334, 2024). "Unpaired analysis also indicated that OVOL1 protein expression was decreased in carcinoma specimens." (PMID 35484112, 2022). "Using two models of prostate and breast cancer mesenchymal cells, we discovered that TFs OVOL1 (OVO-like 1, Entrez Gene ID 5017) and OVOL2 (Gene ID 58495) are associated with MET in our models, as well as in other cancers." (PMID 24124593, 2013). "Our study shows that the ESRPs are regulated by the OVOLs in mesenchymal cancer cells, and that their expression correlates with the OVOLs in the Barretina study: r = 0.76 with OVOL1 and r > 0.81 with OVOL2." (PMID 24124593, 2013). "Our data revealed that silencing OVOL1 markedly reduced the proliferation of these cancer cells." (PMID 40437660, 2025). "Additionally, OVOL1 regulates the stemness of cancer cells, significantly contributing to cancer cell metastasis." (PMID 41459538, 2025). "Yet, we cannot exclude the possibility that OVOL1-mediated MET may potentiate the outgrowth of micrometastases at the last step of cancer metastasis in vivo." (PMID 35484112, 2022). "In addition, the 917 cancer cell-lines in the Barretina study show high correlation between the expression of OVOL1 and OVOL2 (r = 0.76)." (PMID 24124593, 2013). "Furthermore, this analysis identified the same set of genes to correlate positively with either OVOL1 or OVOL2 expression (r > 0.5) in 917 cancer cell lines." (PMID 24124593, 2013). "By elucidating the molecular mechanism by which OVOL1 affects the progression of NSCLC through the cholesterol metabolism pathway, we can provide a novel therapeutic target for treating NSCLC by exploiting the vulnerability of cancer cells associated with metabolic reprogramming." (PMID 40437660, 2025). "Interestingly, these TFs, together with OVOL1/2 (Ovo Like Transcriptional Repressors 1 and 2), had previously been suspected to inhibit epithelial–mesenchymal transition in cancer cells with a hierarchically dominant position for GRHL2, which directly induces expression of EHF and OVOL2." (PMID 41385584, 2025). "The ovo-like transcriptional repressor 1 (OVOL1), a member of the zinc finger protein family of transcription factors, is a critical regulator of both normal epithelial and cancer cell differentiation." (PMID 41230293, 2025). "Mooney and co-workers showed that key regulators of EMT (e.g., ZEB1, SNAI1, and OVOL1/2) represent IDPs and hypothesized that it is their conformational flexibility which enables the formation of highly dynamic protein interaction networks and phenotypic plasticity of cancer cells." (PMID 40889682, 2025). "OVOL1 and SDC1 were also related to activation of several cancer related pathways, such as NOTCH, WNT signaling pathways and focal adhesion." (PMID 37950222, 2023). "It is reported that the TFs OVOL1 and OVOL2 play critical roles in inducing the transition from mesenchymal to epithelial (MET) in several types of human cancers." (PMID 27765529, 2017). "We demonstrate a novel function of two TFs, OVOL1 and OVOL2, as critical inducers of MET in human cancers." (PMID 24124593, 2013).
cancer (continued). "Although OVOL1 did not meet the criteria to be included in the microarray gene signature, the qPCR analysis showed that it is highly upregulated in cancer cells in direct contact with fibroblasts." (PMID 36936987, 2023). "Meanwhile, OVOL1 and OVOL2 are considered critical inducers of EMT/MET in human cancers." (PMID 32106476, 2020). "PTGS2, FN1, CXCL9, CXCL10, ZIC2 e OVOL1 podem desempenhar alguns papéis no carcinoma nasofaríngeo." (PMID 27765529, 2017). "Consequently, a greater knockdown of OVOL1 and OVOL2 would induce a more complete EMT transformation in cancer cells." (PMID 24124593, 2013). "Furthermore, OVOL1 and OVOL2 are co-expressed in multiple cancer cell lines and they induce similar gene expression profiles consistent with MET, which indicate analogous functions." (PMID 24124593, 2013). "The cytokines transforming growth factor-β (TGF-β) and bone morphogenetic proteins (BMP) control the epithelial–mesenchymal plasticity (EMP) of cancer cells, but whether this occurs through interplay with OVOL1 is not known." (PMID 35484112, 2022). "ZIC2 e OVOL1 podem funcionar no carcinoma nasofaríngeo almejando-se de maneira significativa os genes suprarregulados (como o PTGS2, FN1, CXCL9 e CXCL10) na rede reguladora de fator de transcrição - genes diferencialmente expressos (p.ex., ZIC2→PTGS2 e OVOL1→CXCL10)." (PMID 27765529, 2017). "Two of the genes (KIF17 and ATP8A2) showed no methylation in either cancer or matched tissues, and eight genes (EPHA4, OVOL1, UTF1, ADAM8, BOLL, FOXE3, GUCY1A2, and ADCY5) were equally methylated in the two groups." (PMID 21625442, 2011).
tumor (13 papers, 2011 to 2025). "While several transcription factors are implicated in EMT/MET, OVOL1 is of particular interest because of its potential dual role in maintaining epithelial identity and modulating tumor behavior." (PMID 41230293, 2025). "Conversely, the data for nonrecurrent cases established a statistically significant association between OVOL1 expression and the tumor groups (χ2 = 5.5455; p = 0.0185)." (PMID 41230293, 2025). "Statistical analysis demonstrated a significant difference between the two groups (χ2 = 8.64, p = 0.003), with a large effect size (0.5), indicating a strong association between OVOL1 expression and tumor type." (PMID 41230293, 2025). "Regarding tumor recurrence, this study evaluated the association between OVOL1 expression and recurrence in PA and CXPA to explore its potential as a predictor of tumor behavior." (PMID 41230293, 2025). "Our results suggest the potential of OVOL1 as a diagnostic and prognostic biomarker, particularly in distinguishing PA from CXPA, and as a promising indicator of tumor aggressiveness and malignant transformation." (PMID 41230293, 2025). "This suggests that the distinct molecular pathways related to OVOL1 expression differentiate the biological behavior of the two tumor types." (PMID 41230293, 2025). "Next, we used the Transwell assay to explore the migration and invasion of A549 and H1299 cells treated with cholesterol after OVOL1 knockdown, showing that cholesterol treatment promotes tumour cell invasion and migration." (PMID 40437660, 2025). "Immunohistochemical staining results indicated a notable increase in OVOL1 expression in tumour tissues compared to adjacent tissues." (PMID 40437660, 2025). "Accordingly, a detailed investigation of OVOL1 expression in PA and CXPA is expected to contribute to a better understanding of the underlying mechanisms of tumor progression and to improve the assessment of tumor biological behavior." (PMID 41230293, 2025). "High expression of OVOL1 in NSCLC enhanced a variety of tumour features, including proliferation and metastasis." (PMID 40437660, 2025). "Therefore, the observed association suggests that OVOL1 may represent a crucial variable worth tracking in tumor invasiveness, with its differential expression hinting at a nuanced regulatory role in the dynamics of capsular invasion, dissemination, and colonization." (PMID 41230293, 2025). "As the figure shown, P300 was positively related to NDUFAF6 and OVOL1, and negatively related to tumor suppress gene IGFBP6." (PMID 37950222, 2023). "Both ZEB1-shRNA and OVOL1 expression reduced the number of mice with tumor metastasis in multiple sites." (PMID 24124593, 2013). "Notably, the forkhead transcription factor FOXN1, essential for normal cutaneous and thymic epithelial development, and OVOL1, a critical regulator of epithelial lineage determination and differentiation, were downregulated upon tumor occurrence." (PMID 40678065, 2025). "This expression pattern suggests a potential diagnostic utility for OVOL1 in the distinction between PA and CXPA, particularly in morphologically challenging cases, and a possible prognostic relevance in relation to tumor aggressiveness and malignant transformation." (PMID 41230293, 2025). "Given that OVOL1/2 inhibited the expression of EMT-related factors such as vimentin and ZEB1, we hypothesized that knockdown of OVOL1 or OVOL2 may enhance tumor cell invasion." (PMID 32106476, 2020). "In conclusion, our findings suggest that OVOL1 acts as an oncogene in NSCLC, promoting tumour growth and metastasis through the enhancement of cholesterol metabolism." (PMID 40437660, 2025). "Our research has revealed that the downregulation of OVOL1 results in diminished APOE expression both in mRNA and protein levels, which consequently decreases cholesterol uptake by the tumour cells." (PMID 40437660, 2025).
tumor (continued). "Despite these limitations, to our knowledge, this study represents one of the first to comprehensively assess OVOL1 expression in both PA and CXPA, incorporating histopathological subtypes, tumor grade, stage, capsular invasion, and recurrence." (PMID 41230293, 2025). "Low OVOL1 expression was more frequent in high-grade and recurrent CXPA, suggesting a link with tumor aggressiveness." (PMID 41230293, 2025). "Tumour cells in a hybrid E/M state possessed moderated expression levels of GRHL2, OVOL1, ZEB1 and SNAI2." (PMID 36808651, 2023). "The tumour cells in the epithelial state possessed elevated expression levels of GRHL2 and OVOL1, low expression levels of ZEB1 and SNAI2." (PMID 36808651, 2023). "Conversely, tumour cells in the mesenchymal state possessed low expression levels of GRHL2 and OVOL1, high expression levels of ZEB1 and SNAI2." (PMID 36808651, 2023). "Therefore, this study aims to investigate OVOL1 expression in PA and CXPA to clarify its potential role in the transition from benign to malignant lesions and to improve the assessment of tumor biological behavior." (PMID 41230293, 2025). "The statistically significant association and strong effect size (p = 0.005, V = 0.5, respectively) observed between OVOL1 expression and capsular invasion patterns suggest a potential link between this marker and specific mechanisms of tumor aggressiveness, rather than a simple binary role." (PMID 41230293, 2025). "In addition, we determined a prognostic signature with potential clinical applicability and validated PON3 DNA methylation and OVOL1 protein expression as biomarkers with prognostic information independent of tumor thickness and ulceration." (PMID 28578692, 2017). "Therefore, OVOL1 expression appears to be a key variable differentiating the PA and CXPA tumor phenotypes, irrespective of recurrence status." (PMID 41230293, 2025).
OVOL1 also shares sentences with these, for which no sentence is quoted: abscesses (1 paper); adenocarcinoma (1); allergic rhinitis (1); atopic march (1); breast invasive carcinoma (1); Cirrhosis (1); colon cancer (1); colorectal cancer (1); eosinophilic esophagitis (1); epithelial-myoepithelial carcinoma (1); gout (1); hay fever (1); lung adenocarcinoma (1); lymph node metastasis (1); myoepithelial carcinoma (1); Pruritus (1); salivary duct carcinoma (1); skin melanoma (1); squamous cell carcinoma (1).